EGFR (epidermal growth factor receptor)
Diseases named in the same sentence as EGFR in open-access papers (continued):
Sharing a sentence is not in itself a finding about the gene and the disease.
cervical carcinoma (continued). "Moreover, Afatinib or Erlotinib triggered cell death in CaSki cells (from 0.84% to 12.47% and from 0.84% to 9.80%, respectively), confirming that EGFR signalling is critical for cell survival in cervical cancer cells." (PMID 25366117, 2014). "One may indeed expect KIAA1199 to directly interfere with pro-apoptotic, Plexin A2-dependent cascades as we demonstrated an additive effect between Semaphorin 3A and EGFR inhibition in triggering apoptosis in cervical cancer cells." (PMID 25366117, 2014). "EGFR has recently been identified as a promising target for cervical cancer." (PMID 24860830, 2014). "Collectively, our study highlights a novel function for TACC3 in EGF-mediated EMT process and suggests that targeting of TACC3 may be an attractive strategy to treat cervical cancers driven by EGF/EGFR signaling pathways." (PMID 23936413, 2013). "The expression of EGFR has been found to be overexpressed in cervical cancer." (PMID 23936413, 2013). "Thus, it seems unlikely that HPV16 oncoproteins are acting through the EGFR signaling pathway in cervical cancer cells." (PMID 23967226, 2013). "In conclusion, this study demonstrated that the compounds effectively inhibited proliferation and invasion of HeLa cells and suggests that EGFR may be a potential therapeutic agent for cervical cancer." (PMID 23706036, 2013). "In addition, we compared the phenotypes in cultured cervical cancer cells with various EGFR expression levels after treatment with the potent EGFR inhibitor AG1478." (PMID 21730982, 2011). "It is unclear whether EGFR amplification is a feature of adenocarcinomas and adenosquamous carcinomas, which comprise 10–25% of cervical cancers." (PMID 21730982, 2011). "Preclinical studies developed on cervical cancer cell lines confirm even in this tumor the results obtained in murine model from Baselga group: both chemo and radiotherapy join of cetuximab coadministration effects but apparently in a less EGFR-dependent way." (PMID 22235224, 2011). "It is uncertain whether results on EGFR function in H&N cancer can be extrapolated to cervical cancer; however, both are squamous type carcinomas and both have an HPV-related aetiology, suggesting that there might be activation of common molecular features." (PMID 22091418, 2011). "Sensitivity of cervical cancer cells to AG1478 depended on the presence of EGFR overexpression." (PMID 21730982, 2011). "This cell line constitutes a pre-clinical model that represents a broad spectrum of HPV positive cervical cancer patients that, according to our results, could benefit by a combination of anti-EGFR based therapies and PI3K-Akt inhibitors." (PMID 22185378, 2011). "Furthermore, we found that the frequency of EGFR overexpression in lymph node metastases was approximately as high as in the primary lesions of cervical cancer." (PMID 18700025, 2008). "Studies on the EGFR status of metastatic lymph node of cervical cancer will provide precious knowledge to evaluate whether the receptor is of interest for diagnostic and/or therapeutic procedures or not." (PMID 18700025, 2008). "Overexpression of EGFR in cervical cancer has been reported to be common (ranges from 26–72%)." (PMID 18700025, 2008). "However, the association among lncRNA, miRNA, and EGFR in cervical cancer has not been widely probed." (PMID 39574469, 2024). "In conclusion, our findings reveal an inverse association between RKIP and EGFR expression across various solid tumors, shedding new light on the underlying molecular mechanisms contributing to the aggressive phenotype associated with RKIP and EGFR in cervical cancer." (PMID 38927888, 2024). "First, in such lines, even in the absence of mutations in the EGFR gene itself, the genes related to proliferation, transcription and DNA repair are often upregulated compared with normal tissues, as it was shown for cervical carcinoma line HeLa." (PMID 37686213, 2023).
cervical carcinoma (continued). "These discrepancies in relation to EGFR as a predictor of outcome in cervical cancer patients may be due to the variety of techniques and scoring systems used, lack of standardised assays and the different reagents used as well as the sample size and heterogeneity of the samples." (PMID 38414930, 2023). "This large range in the overexpression of EGFR cervical cancer tissue samples may be due to differences in the study’s methodology (scoring systems used, techniques used, detection methods, lack of standardised assays, assay cutoff points and the type of EGFR clones used)." (PMID 38414930, 2023). "Therefore, we hypothesized that autophagy-mediated EGF secretion might induce cisplatin resistance by activating EGFR signaling in cervical cancer." (PMID 37165076, 2023). "Although there is no strong evidence, most Indian women are historically non-smokers; hence, individuals with cervical cancer may have EGFR mutations frequently." (PMID 37310466, 2023). "So far, there has been little research on the role of naturally occurring EGFR subtypes, and few studies have shown that other subtypes (such as secreted EGFR or sEGFR) are secreted in the plasma and may be prognostic for lung and cervical cancer." (PMID 35662687, 2022). "Furthermore, HPV E6/E7 oncoproteins in combination with EGF promote cervical cancer cell proliferation, and HPV E6 causes prolonged tyrosine receptor signaling, resulting in the internalization of phosphorylated receptors, such as EGFR protein." (PMID 36358752, 2022). "Furthermore, EGFR expression has been correlated with poor survival among cervical cancer patients." (PMID 33886813, 2021). "Because Eppk1 is a part of EGFR, and Eppk1 expression has a positive correlation with EGFR in CC from TCGA data (P < 0.05, R = 0.13), we further clarify the EGFR-related signaling pathways by which Eppk1 expression affects the proliferation of cervical cancer cells." (PMID 33827480, 2021). "Hence, the authors proposed that combined targeting of the Hippo and the EGFR pathways might constitute a novel therapeutic strategy for treatment of cervical cancer." (PMID 34206026, 2021). "Additionally, a high level of expression of EGFR was found to be correlated with a high density of Ki-67 positively-stained nuclei in severe dysplasia and carcinoma in situ, indicating a high proliferative state of cervical cancer cells." (PMID 31470515, 2019). "Thus, we evaluated whether EGFR was activated by CSC in the cervical cancer cell-derived CaSki and SiHa cell lines." (PMID 30619121, 2018). "In this context, we examined whether PAR1 or PAR2 transactivated EGFR in cervical cancer cells." (PMID 30093972, 2018). "Therefore, the inhibition of ATXN1 and ATXN1-mediated activation of the EGFR–MAPK signaling pathway may play an important role in the treatment of cervical cancer." (PMID 29212253, 2017). "However, treatment with cetuximab (CET) (chimeric IgG1, anti-EGFR mAb) as monotherapy or CET in combination with chemotherapy was ineffective in patients with cervical cancer, in spite of the apparent absence of activating mutations in the EGFR pathway." (PMID 27783105, 2017). "Thus, it is essential that more should be performed to determine whether EGFR overexpression is a prognostic factor for cervical cancer patients in Asia and other regions." (PMID 27438047, 2016). "Therefore, the activation of the EGFR/AKT2/CCND1 signaling pathway induced by HPV16 E6-deprivated miR-2861 expression in cervical cancer cells may, at least partially, explain the tumor suppression effects of miR-2861 in cervical cancer." (PMID 27364926, 2016). "Therefore, we performed this meta-analysis to determine whether EGFR overexpression could predict prognoses in cervical cancer patients." (PMID 27438047, 2016). "However, data related to the effect of EGFR inhibitors on cervical cancer remain inconclusive." (PMID 27438047, 2016).
cervical carcinoma (continued). "In addition, the involvement of EGFR pathway in YAP regulating cervical cancer cell growth is further evidenced by the observation that treatment of ME180-YAP and ME180-YAPS127A cells with AG1478 (EGFR inhibitor) dramatically blocked their ability to form colonies in the soft agar (Fig8D)." (PMID 26417066, 2015). "The synergetic suppressive effect of AG1478 and verteporfin on the growth of ME180-YAP and ME180-YAPS127A cells and secretion of AREG clearly indicates that combined targeting of Hippo/YAP and EGFR pathways may represent a novel therapeutic strategy for cervical cancer (Figs8 and EV5)." (PMID 26417066, 2015). "EGFR expression in cervical cancer may also be activated by HPV16 E5 or E6/E7 proteins." (PMID 26209091, 2015). "As Plexin A2 deficiency enhanced Semaphorin 3A-dependent EGFR phosphorylations and also increased KIAA1199 protein levels, KIAA1199 acts as a pro-survival protein, at least by promoting EGFR signalling to limit Semaphorin 3A- and Plexin A2-mediated cell death in cervical cancer cells." (PMID 25366117, 2014). "No data is available on EGFR variant III in cervical cancer." (PMID 22091418, 2011). "On the basis of these findings, cetuximab therapy may be efficacious in cervical carcinoma patients who have EGFR protein overexpression without KRAS mutations, particularly those who have not responded to standard treatment modalities." (PMID 21730982, 2011). "The cytotoxicity of the fusion toxin was clearly target receptor specific because free EGF could effectively block this effect and, moreover, for all the cervical carcinoma cell lines tested, a clear correlation between EGFR expression and sensitivity to the SE fusion toxin could be observed." (PMID 22069572, 2010). "Our study demonstrates that dihydrocapsaicin (DHC) significantly enhances TNF-α-induced G1 cell cycle arrest and apoptosis in HeLa cervical cancer cells by targeting the TAK1-mediated NF-κB and EGFR survival pathways." (PMID 40507823, 2025). "This pathway interacted with EGFR signaling and HPV oncoproteins to regulate the malignant development of cervical cancer." (PMID 39856747, 2025). "Head-and-neck studies implicate EGFR signaling in both radio-tolerance and EGFR-TKI insensitivity, yet direct evidence in cervical cancer has been limited." (PMID 41156200, 2025). "In cervical cancer, the TF-PAR-2 pathway mediates cisplatin resistance through an epidermal growth factor receptor (EGFR)- and COX2-dependent mechanism." (PMID 38719932, 2024). "BING ZHAO and MENGCAI HU demonstrated in their study on cervical cancer cells that gallic acid exhibits inhibitory effects on the expression of ADAM17, EGFR, p-AKT, and p-ERK, thereby effectively impeding the progression of cervical cancer." (PMID 39045282, 2024). "The interaction of the Hippo pathway with EGFR signaling and HPV oncoproteins in the progression of cervical cancer was reported in 2015." (PMID 38607003, 2024). "The main objective of the study was to determine the prevalence of EGFR or HER1 and HER2 protein expression in cervical cancers and to determine their impact on overall survival." (PMID 38414930, 2023). "MiR‐125a‐5p, for example, inhibits cervical cancer cell proliferation both in vivo and in vitro by targeting GALNT7 to inhibit the signaling cascade EGFR/PI3K/AKT after significantly down‐regulating such miRNA in cervical cancer cells." (PMID 36305754, 2023). "The aim of this study was to determine if EGFR and HER2 proteins were overexpressed in cervical cancer tissue samples and their relation to the survival of indigenous African cervical cancer patients." (PMID 38414930, 2023). "Several signaling mechanisms for regulating PTGS2 in cervical cancer have been validated, including the EGF and nuclear factor κB (NF-κB) pathways, and PAR2 through an EGFR-dependent mechanism." (PMID 36765810, 2023).
cervical carcinoma (continued). "Studies on epidermal growth factor receptor 1 (EGFR or HER1) and human epidermal growth factor receptor 2 (HER2 neu) have been investigated in Caucasian and Asian patients with cervical cancer." (PMID 38414930, 2023). "EGFR/PTEN/mTOR-pathway activation and ER expression appear closely intertwined in cervical cancer, as previously observed in other solid tumors." (PMID 37623437, 2023). "Another treatment for cervical cancer is targeted therapy, which inhibits the cyclooxygenase-2 (COX-2) and epidermal growth factor receptor (EGFR)." (PMID 37720346, 2023). "In cervical cancer experiments, PD153035 treatment led to a significant suppression of EGFR expression, as well as the phosphorylation of PI3K and AKT." (PMID 37633093, 2023). "Studies from elsewhere have demonstrated the relationship between epidermal growth factor receptor (EGFR) and human epidermal growth factor receptor 2 (HER2) and advanced cervical cancer." (PMID 38414930, 2023). "One study has illustrated HPV E6 oncogene activated JNK1/2 phosphorylation and demonstrated a positive feedback loop between JNK-dependent activation of the EGFR pathway and HPV E6/E7 expression in cervical cancer." (PMID 35454780, 2022). "Recently, immunotherapy agents have been suggested for cervical carcinomas, such as anti-CTLA-4, anti-PD-1, anti-PD-L1, anti-VEGF, and anti-EGFR agents." (PMID 36276117, 2022). "In cervical cancer cells, the HPV early gene product, HPV 16E5, modulates the ligand-dependent activation of EGFR in EGFR overexpression." (PMID 36358752, 2022). "Overall, the scientific data show that resveratrol has the ability to target/inhibit certain signaling molecules (EGFR, VEGFR, PKC, JNK, ERK, NF-kB, and STAT3) involved in cervical cancer cell proliferation and survival." (PMID 36558430, 2022). "EGFR, like OSMR, is also known as a biomarker for cervical cancer and induces tumor progression and activation of STAT3." (PMID 36551576, 2022). "In addition, a study demonstrated that the interaction of the E6 oncoprotein could also cause a decrease in the expression of a tsmiR, by which HPV16 E6 is able to decrease the level of miR-2861 expression, resulting in the suppression of the EGFR/AKT2/CCND1 pathway in cervical cancer cells." (PMID 33803022, 2021). "Together, our data indicate that impaired EGFR/ErbB signalling contributes, in part, to the proliferative defects observed in HPV+ cervical cancer cells upon inhibition of JNK signalling." (PMID 33303976, 2021). "In summary, a new regulatory network was found, employing HPV16 E6, miR-2861, and the EGFR/AKT2/CCND1 signaling pathway to syntonize proliferation, apoptosis, and invasion in cervical cancer cells." (PMID 33803022, 2021). "Various circRNAs (such as circSLC26A4, circ-ATP8A2) promoted the oncogenesis of cervical cancer by increasing the downstream mRNAs, including HOXA1 and EGFR via sponging miRNAs." (PMID 34596142, 2021). "Activated YAP triggers the amplification of EGFR, AREG and TGFα, and therefore a positive loop is formed that promotes cervical cancer progression." (PMID 33467099, 2021). "A recent study showed that the E6 oncogene of HPV activates JNK1 signalling to promote cell proliferation and metastasis in cervical cancer, partially from JNK1 upregulating epidermal growth factor receptor (EGFR) signalling." (PMID 34943783, 2021). "Another therapy is targeted therapy, which regulates epidermal growth factor receptor (EGFR) and cyclooxygenase-2 (COX-2) for treating cervical carcinoma." (PMID 33466408, 2021). "Since all these intronic RNAs are upregulated in both ESCC cell lines, their possible roles in EGFR gene in ESCC, as in cervical cancer, need to be further investigated." (PMID 34722266, 2021).
cervical carcinoma (continued). "According to a 2015 study, TGFa and amphiregulin, via EGFR, inhibit the Hippo signaling pathway and activate YAP, to induce cervical cancer cell proliferation and migration." (PMID 34206026, 2021). "In cervical cancer cells, AST reduced the expression of EGFR and interfere with EGF binding, thereby inducing apoptosis." (PMID 33509300, 2021). "Further investigation into the potential use of EGFR inhibitors, PAF antagonists and LPCAT inhibitors in the treatment of cervical cancer is needed through preclinical and clinical studies." (PMID 33392068, 2020). "We also showed that the combined inhibition of EGFR and PAFR has great therapeutic potential in cervical cancer cells that express these receptors." (PMID 33392068, 2020). "In the current study, we showed a significant positive correlation between EGFR and PAFR, and between EGFR and LPCAT2 in 306 cervical cancer samples deposited in TCGA database." (PMID 33392068, 2020). "In conclusion, miR-125a-5p suppressed cervical cancer progression by post-transcriptionally downregulating GALNT7 and inactivating the EGFR/PI3K/AKT pathway." (PMID 32308562, 2020). "Herein, we identified EGFR, LPCAT2, and PAFR as targets for cervical cancer therapy, using TCGA-based in silico analyzes." (PMID 33392068, 2020). "Taken together, our data suggest that EGFR, LPCAT2, and PAFR emerge as novel targets for cervical cancer therapy." (PMID 33392068, 2020). "Collectively, we proposed that EGFR, LPCAT2, and PAFR emerge as novel targets for cervical cancer therapy." (PMID 33392068, 2020). "IHC analysis indicated that known protein biomarkers currently available for cervical cancer subtype screening (Ki67, P16INK4A, deltaNp63, EGFR, and Pan KRT) were highly expressed in cervical cancer tissues from the KRT14-YAPS127A mice." (PMID 30840887, 2019). "Clinically, it has been shown that levels of EGFR and human papilloma virus (HPV)-E6 and E7 proteins are increased in the cervical epithelial cells of HPV-positive women with cervical cancer." (PMID 31470515, 2019). "Recent studies have suggested that the NF-κB, ERK1/2, PI3 K/Akt, EGFR, and PKA signaling pathways are important in the migration and invasion of cervical cancer cells." (PMID 31572058, 2019). "To examine the clinical relevance of the MUC1-EGFR-IL-6 axis in cancer patients, we collected 20 paired pre- and post-NACT tumor specimens from cervical cancer patients and performed immunohistochemistry to detect the expression of MUC1, EGFR, and IL-6." (PMID 31772161, 2019). "In cervical cancer, PIK3CA (33.3%), PD1 (26.7%), and EGFR (20%) were most common, whereas PD1 (40%) was most common in vulvar cancers." (PMID 30848097, 2019). "In turn, TGFα and AREG, via EGFR signaling, suppressed the Hippo pathway and activated YAP protein (dephosphorylated LATS1, MOB1, and YAP1) to promote cervical cancer cell growth." (PMID 30840887, 2019). "A study in cervical cancer excluded a role for TSPAN1 in focal adhesion kinase (FAK), phosphoinositide-3-kinase (PI3K) and in EGFR-dependent signalling to the RAS/ERK pathway, arguing against a role for TSPAN1 as a mediator of cell surface receptor signalling." (PMID 28701765, 2017). "Consistently, in this study, we found that EGFR and VEGF expression were markedly increased in CD73 transfected cervical cancer cells." (PMID 28202050, 2017). "In conclusion, this study provides a rationale to initiate a clinical trial for cervical cancer with adoptively transferred allogeneic NK cells, employing either UCB-NK or PBNK + CET for EGFR-expressing tumors." (PMID 27783105, 2017). "As Akt is an important downstream signaling molecule of EGFR and VEGF, we also investigated the change of Akt expression in CD73 overexpression cervical cancer cells." (PMID 28202050, 2017).